KAT5 (lysine acetyltransferase 5)
Diseases named in the same sentence as KAT5 in open-access papers (continued):
Sharing a sentence is not in itself a finding about the gene and the disease.
rheumatoid arthritis (3 papers, 2023 to 2024). A chronic, systemic autoimmune disorder characterized by inflammation in the synovial membranes and articular surfaces. "For example, KAT5 was lowly expressed in rheumatoid arthritis T cells, which affected regulatory T cell function via reducing Foxp3 acetylation level." (PMID 38561411, 2024). "Previous studies have suggested that KAT5 contributes to chronic inflammatory responses, such as rheumatoid arthritis (RA) and allergy, by regulating the Foxp3 expression in regulatory T cells and STAT6 expression in B cells, respectively." (PMID 38110429, 2023).
thyroid cancer (3 papers, 2021 to 2024). "It has been recently reported that the KAT5 served as a transcriptional partner of FOSB to potentiate thyroid cancer growth and metastasis by enhancing FOSB-mediated transcriptional activation of DPP4." (PMID 39164746, 2024). "KAT5 dysregulation correlated with more advanced-stage and poorer outcomes of thyroid carcinoma patients." (PMID 37342240, 2022). "In this study, we first assessed the expression levels of KAT5 in human thyroid carcinoma, and the TCGA database was downloaded." (PMID 37342240, 2022). "First, the Cancer Genome Atlas (TCGA) dataset was used to detect the relationship between KAT5 expression and outcomes of thyroid carcinoma patients." (PMID 37342240, 2022). "KAT5 enhances metastasis and invasion by stabilizing c-MYC in thyroid cancer." (PMID 34406978, 2021).
acute kidney injury (2 papers, 2022 to 2024). Sudden and sustained deterioration of the kidney function characterized by decreased glomerular filtration rate, increased serum creatinine or oliguria. "In contrast, KAT5 in proximal tubular cells prevents acute kidney injury via glomerular filtration regulation by an epigenetic mechanism as well as promotion of DNA repair, indicating the cell type-specific action and roles of DNA repair factors." (PMID 35024974, 2022). "PT cell-specific KAT5 knockout mice present mild tubular damage without elevated serum creatinine, whereas podocyte-specific KAT5 knockout mice show massive albuminuria and renal failure." (PMID 35024974, 2022). "It has been demonstrated that KAT5 plays an important role both in promoting DNA repair and in attenuating tubuloglomerular feedback (TGF) in an ischemic reperfusion (IR) induced-acute kidney injury (AKI) model in mice." (PMID 35024974, 2022).
Autoimmunity (2 papers, 2019 to 2025). The occurrence of an immune reaction against the organism's own cells or tissues. "In addition, mice with conditional deletion of Tip60/Kat5 in their Tregs develop lethal autoimmunity in early life." (PMID 31003455, 2019).
peritonitis (2 papers, 2023 to 2024). Inflammation of the peritoneum (tissue that lines the abdominal wall and covers most of the organs in the abdomen). "Earlier research indicates that a loss or reduction of KAT5 function may alleviate systemic inflammatory responses in MSU-induced peritonitis models, commonly linked with gout or urate deposition." (PMID 39161423, 2024). "Consistently, KAT5 deficiency attenuates the systemic inflammatory responses in LPS-induced endotoxin shock model and MSU-induced peritonitis model." (PMID 38110429, 2023).
Cerebellar atrophy (1 paper, 2025). Cerebellar atrophy is defined as a cerebellum with initially normal structures, in a posterior fossa with normal size, which displays enlarged fissures (interfolial spaces) in comparison to the foliae secondary to loss of tissue. "Mutations in the TIP60/KAT5 gene are associated with a neurodevelopmental syndrome characterized by progressive cerebellar atrophy, developmental delays, and intellectual disabilities." (PMID 41227365, 2025).
glomerulosclerosis (1 paper, 2022). A hardening of the kidney glomerulus caused by scarring of the blood vessels. "Recently, we demonstrated that the DNA DSB repair factor KAT5, which acts coordinately with KLF4, is indispensable for maintaining healthy podocytes and that loss of KAT5 in podocytes causes massive proteinuria and glomerulosclerosis with increased DNA damage sites and DNA methylation in podocytes." (PMID 35024974, 2022).
gout (1 paper, 2024). A condition characterized by painful swelling of the joints, which is caused by deposition of urate crystals. "KAT5, from the MYST acetyltransferase family, significantly influences various cellular activities and was associated with a reduced risk of gout in our study." (PMID 39161423, 2024). "Elevated expression of KRTCAP2 and PGAP3 is linked to an increased risk of gout, whereas higher expression of THBS3, THBS3-AS1, and KAT5 is associated with a reduced risk of the disease." (PMID 39161423, 2024). "Notably, increased expression of KRTCAP2 and PGAP3 is associated with an increased risk of gout, whereas increased expression of THBS3, THBS3-AS1, and KAT5 is associated with a reduced gout risk." (PMID 39161423, 2024).
Hyperglycemia (1 paper, 2021). An increased concentration of glucose in the blood. "A DNA repair factor lysine acetyltransferase 5 (KAT5) was found to be essential for the maintenance of the podocyte genomic integrity and hyperglycemia was shown to decrease the expression of KAT5 as well as to increase DNA damage in podocytes." (PMID 33467659, 2021).
Insulin resistance (1 paper, 2023). Increased resistance towards insulin, that is, diminished effectiveness of insulin in reducing blood glucose levels. "Several bona fide GSK3 substrates displayed impaired dephosphorylation across insulin resistance models, such as S641 on glycogen synthase (CI and AA), and S86 and S90 on the histone acetyltransferase Kat5 (CI, DEX, TNF, and AA)." (PMID 36808134, 2023).
male infertility (1 paper, 2025). The inability of the male to effect fertilization of an ovum after a specified period of unprotected intercourse. "Collectively, our findings highlight an essential role of APBB1/KAT5/GDF15 in governing human SSC fate decisions and maintaining normal spermatogenesis and underscore them as therapeutic targets for treating male infertility." (PMID 40151319, 2025).
Obesity (1 paper, 2025). Accumulation of substantial excess body fat. "A common point has been the link of PCa biomarkers, obesity-related factors, as well as KAT5, PRKCA, and SUMO1 to NF-kB, a transcription factor, involved in proliferation, inflammation, and apoptosis, all tumor-promoting processes." (PMID 40481981, 2025).
orofacial cleft (1 paper, 2023). A disorder of facial skeleton that is characterized by cleft lip and/or cleft palate that result in feeding, speech and hearing problems caused by failures during development. "Given the causal link with both syndromic and non-syndromic forms of orofacial clefts, we here decided to study the molecular function of Kat5 in the cranial neural crest and the facial mesenchyme." (PMID 37024457, 2023). "In addition, KAT5 has also been reported to be a quantitative trait locus and risk factor for non-syndromic forms of orofacial clefting because of the presence of single nucleotide polymorphisms in the vicinity of the gene." (PMID 37024457, 2023). "In case of heterozygous neural crest-specific Kat5 mutations, this leads to orofacial clefts." (PMID 37024457, 2023).
triple-negative breast carcinoma (1 paper, 2016). An invasive breast carcinoma which is negative for expression of estrogen receptor (ER), progesterone receptor (PR), and human epidermal growth factor receptor 2 (HER2). "A multi-parametric RNAi screening approach was developed to identify new EMT regulators such as KAT5 in the triple negative breast cancer cell line MDA-MB-231." (PMID 27581651, 2016).
cancer (93 papers, 2011 to 2025). A tumor composed of atypical neoplastic, often pleomorphic cells that invade other tissues. "Numerous KAT5 mutations have been identified in cancer cells and in this work we used established artificial intelligence algorithms to classify them as predicted pathogenic or driver." (PMID 36530474, 2022). "We investigated the distribution of KAT5 point mutations in the reported cancers using the Catalogue of Somatic Mutations in Cancers (COSMIC)." (PMID 36530474, 2022). "Here we undertook a pan cancer analysis to investigate mutations within the KAT5 gene in cancer cells." (PMID 36530474, 2022). "Therefore, KAT5 mutations in cancer cells can affect both DNA damage repair and gene expression." (PMID 36530474, 2022). "Beyond p300, the Kat5/TIP60 family has gained attention for its roles in cancer and potential in cardiac fibrosis." (PMID 40426997, 2025). "We and others have also shown that KAT5 and PRMT5 mutations are endemic in human cancers, which have destabilized DSB repair machineries." (PMID 39874873, 2025). "In hepatocarcinoma, O-GlcNAcylation of lysine acetyltransferase 5 (KAT5) is critical for cancer cell migration, invasion, and metastasis." (PMID 37838167, 2023). "Lysine acetyltransferase 5 (KAT5), an acetylase that has been shown to induce the acetylation of both histone and non-histone proteins, has been shown to be a potential target for cancer treatments." (PMID 38299150, 2023). "KAT5 is one of the most important lysine acetyltransferases (KATs), which has recently been suggested as a potential therapeutic target for cancers, such as breast and colon cancers." (PMID 35333774, 2022). "Numerous studies have confirmed the function of KAT5 on cancer cell proliferation, invasion and migration." (PMID 35383533, 2022). "Changes in KAT5 gene expression has been correlated with cancer progression and small molecule inhibitors targeting KAT5 have already been developed." (PMID 36530474, 2022). "KAT5 is one of the most crucial lysine acetyltransferases, which has recently been suggested as a potential therapeutic target for cancers, such as colon and breast cancers." (PMID 35392432, 2022). "It is reported that KAT5 is capable of stabilizing the oncogene c-Myc, that is critical for development of several cancers such as breast cancer and anaplastic thyroid cancer (ATC)." (PMID 34406978, 2021). "Moreover, in anaplastic thyroid carcinoma, lysine acetyltransferase 5 is overexpressed and promotes the proliferative activity of cancer cells while repressing apoptosis and the induction of autophagy by inducing KSP expression." (PMID 41009541, 2025). "~22% of KAT5-bound genes are common essential in cancer cell lines (depmap.org) and significantly overlap Myc bound genes in mouse ESCs28 and MYC and E2F-transcription factor network targets, many of which have critical roles in cell cycle entry, S-phase, and mitosis." (PMID 40346033, 2025). "KAT5 is an acetyltransferase that shows distinct functions in different cancers." (PMID 38453820, 2024). "The expression of KAT5 was downregulated in colon, lung, breast, and other cancers." (PMID 37365518, 2023). "Studies have reported the important function of KAT5 in cancer initiation and progression." (PMID 35392432, 2022). "Recent studies have reported that TWIST can be acetylated by KAT5 in cancer metastasis." (PMID 34650217, 2021). "These novel SNPs in the KAT5 and NR3C1 genes warrant confirmation, and additional functional studies are needed to assess the functional consequences of the mutations and their relationship to cancer, such as whether the SNPs would mimic the epigenetic regulations of these genes." (PMID 23940558, 2013).
cancer (continued). "Furthermore, the chromatin remodeler p400 is overexpressed in some cancers and promotes oncogenic WNT signaling and counteracts the tumor-suppressive function of the histone acetyltransferase KAT5." (PMID 37958827, 2023). "Additionally, levobupivacaine administration inhibited the expression of KAT5, which epigenetically regulated the acetylation of MAFB and subsequently cancer cell stemness." (PMID 35333774, 2022). "As one of the first acetyltransferase that induce acetylation of both histone and nonhistone proteins, KAT5 has emerged as a promising therapeutic target in cancer treatment." (PMID 35602291, 2022). "Lysine acetyltransferase 5 (KAT5) acetylates both non-histone and histone proteins and increases the invasiveness of cancer cells." (PMID 36110954, 2022). "KAT5/TIP60-driven lactylation of PIK3C3/VPS34 at lysine residues 356 and 781 enhances its interaction with BECN1, ATG14, and UVRAG, promoting autophagy that may contribute to cancer progression." (PMID 39979245, 2025). "TIP60 (also known as acetyltransferase 5 (KAT5)) is involved in chromatin remodeling, gene regulation, DNA repair, cancer development, and tumorigenesis by acetylating histone or nonhistone proteins." (PMID 40612865, 2025).
tumor (86 papers, 2010 to 2025). "Furthermore, TIP60 expression correlated with tumor stage, and analysis of ccRCC patient data from the TCGA database showed that lower TIP60 (KAT5) mRNA levels are associated with poorer survival." (PMID 40858596, 2025). "As a result, we performed scRNA-seq analysis of tumors derived from GSC-0827 and GSC-464T isolates and then mapped in vitro KAT5 and Control KO cells from scRNA-seq data onto their respective in vivo tumor references." (PMID 40346033, 2025). "We used one such clone, #13 (C13), which demonstrated key characteristics including Dox-dependent KAT5 expression, requirement of Dox+ for continued growth, and competent tumor initiation potential in the presence of Dox." (PMID 40346033, 2025). "KAT5 inactivation significantly decreases tumor progression and invasive behavior while increasing survival after standard of care." (PMID 40346033, 2025). "In undifferentiated thyroid carcinoma, KAT5 can also stabilise c‐myc through acetylation, promoting tumour invasion and metastasis." (PMID 39778006, 2025). "KAT5 is a tumor suppressor that is found to be repressed in early stages of CRCs and breast cancers." (PMID 36979914, 2023). "Ectopic expression of KAT5 and PD-L1 reversed the function of abrine on tumor growth and T cell function." (PMID 35602291, 2022). "Our previous study reported that overexpression of KAT5 is associated with poorer survival and tumor metastasis in ATC and showed that KAT5 acetylates and stabilizes c-Myc by blocking proteasome." (PMID 37342240, 2022). "Expression of c-Myc is enhanced and deregulated in many human tumors, suggesting a possibility that highly expressed KAT5 in ATC contributes to the progression of tumor by modulating c-Myc." (PMID 37342240, 2022). "Based on 82 ATC clinical samples, our previous study found a strong correlation of lysine acetyltransferase 5 (KAT5, also known as Tip60) overexpression with poorer prognosis and tumor metastasis of ATC." (PMID 37342240, 2022). "Previous studies have reported that KAT5 acetylates c-Myc, thereby increasing its stability and promoting tumor metastasis." (PMID 34650217, 2021). "In summary, the clinical validation supported the findings that PCK1 suppresses KAT5 O-GlcNAcylation and inhibits tumor metastasis in human primary HCC." (PMID 34650217, 2021). "KAT5 was involved in HCC tumor cell growth and promoted EMT by acetylation of the SPZ1-TWIST1 complex." (PMID 34650217, 2021). "While this supports a mechanism for tumour progression requiring Tip60 down regulation, we did observe a very low rate of Kat5 gene amplification (1.6%)." (PMID 30846725, 2019). "Through an unbiased genetic screen, we found that heterozygosity for Enhancer of Polycomb [E(Pc)], a component of the Tip60 lysine acetyltransferase complex (also known as KAT5 in humans), significantly increased tumor burden in hopTum animals." (PMID 31072879, 2019). "Moreover, attenuating KAT5 expression followed by standard of care (temozolomide + fractionated radiation) significantly reduced tumor growth post-SOC and provided a significant survival benefit." (PMID 40346033, 2025). "Moreover, titrating KAT5 activity in GSCs concomitantly attenuates G0 egress, protein synthesis, and tumor growth, revealing a dynamic interplay between cell cycle, growth regulation, and KAT5 activity." (PMID 40346033, 2025). "However, it seems likely there is therapeutic window for KAT5 inhibition given its increased activity in high grade tumors and also likely addiction to protein synthesis in KAT5hi tumor cells." (PMID 40346033, 2025). "Thus, it seems likely that MYC and KAT5/Tip60 have causal roles in regulating protein synthesis and promoting HHT sensitivity in HGG tumor cells." (PMID 40346033, 2025). "The expression of KAT5 was weakly correlated with tumor infiltrating lymphocytes." (PMID 37365518, 2023). "KAT5 and KAT6A were associated with prognosis and tumor mutation burden in KIRC." (PMID 37365518, 2023).